ANXA1 (annexin A1)
Diseases named in the same sentence as ANXA1 in open-access papers (continued):
Sharing a sentence is not in itself a finding about the gene and the disease.
atherosclerosis (20 papers, 2015 to 2024). A disease characterized by the build-up of fatty material and calcium deposition in the arterial wall resulting in partial or complete occlusion of the arterial lumen. "In specifically T lymphocytes, ANXA1 is conversely an important modulator of proinflammatory functions, with evidence of ANXA1 decreasing the risk of atherosclerosis in humans." (PMID 38443832, 2024). "A protective role has been implicated for ANXA1 in atherosclerosis in a study showing that the ANXA1 synthetic N‐terminal peptide, Ac2‐26, is able to reduce neutrophil and monocyte‐mediated atherosclerotic plaque formation." (PMID 35146757, 2022). "In fact, AnxA1 polarized macrophages toward an anti-inflammatory phenotype, which has been associated to beneficial/protective effects in atherosclerosis and CVD." (PMID 36313572, 2022). "Several recent reviews have described the role of Annexin A1 in the cardiovascular system, including its pro-resolving role in inflammation associated with atherosclerosis and myocardial infarction." (PMID 34943928, 2021). "Atherosclerosis is another disease mediated by innate immune cell involvement, and a protective role for ANXA1 in modulating this disease has been widely explored." (PMID 35146757, 2022). "ANXA1 has been shown to inhibit the development of atherosclerosis via an anti-inflammatory reaction." (PMID 35748965, 2022). "Regarding the cardiovascular system, major areas of investigation include the role of Annexin A1 in vascular abnormalities, atherosclerosis, and myocardial infarction." (PMID 34943928, 2021). "In conclusion, among cardiovascular disorders, considerable information is available regarding the role of Annexin A1 with respect to atherosclerosis and myocardial infarction where potentiating Annexin A1 signaling seemingly exerts beneficial outcomes." (PMID 34943928, 2021). "We expect to promote the study of the role of ANXA1 in atherosclerosis and sincerely hope that more scientists will study the relationship of ABCA1 with ANXA1 and atherosclerosis development." (PMID 32894039, 2020). "In this article, we review the roles of ANXA1 in atherosclerosis and focus on the crosstalk of ABCA1 and ANXA1." (PMID 32894039, 2020). "Although ABCA1 mediates ANXA1 release, the effect of this function on atherosclerosis has been unclear." (PMID 32894039, 2020). "ANXA1 is also a specific marker of microparticles, and accumulating evidence has shown that ANXA1 plays a key role in inhibiting the development of atherosclerosis via an anti-inflammatory reaction." (PMID 32894039, 2020). "On the other hand, AnxA1 or AnxA1-related peptides counteract non-alcoholic steatohepatitis, as well as atherosclerosis and cardiovascular disease triggered by hyperlipidemia." (PMID 30110341, 2018). "As an important modulator in atherosclerosis, ANXA1 can inhibit not only the monocyte adhesion to endothelium but also the expression of inflammatory enzymes, such as inducible cyclooxygenase 2 (COX-2) and phospholipase A2." (PMID 28035059, 2017). "One such glucocorticoid product, annexin A1, enhances efferocytosis, resolves inflammation, and delays atherosclerosis in mice." (PMID 29379788, 2017). "We conclude that progression of atherosclerosis can be attenuated pharmacologically with hr-anxA1 in a murine model of atherosclerosis." (PMID 26090792, 2015). "Role of and therapeutic potential of Annexin A1 in atherosclerosis." (PMID 34943928, 2021).
atherosclerosis (continued). "Many studies suggest that exosomes could be used for not only the diagnosis but also the treatment of atherosclerosis, but whether the interaction of ANXA1 with exosomes also regulates atherosclerosis progression needs to be further studied." (PMID 32894039, 2020). "Given that ANXA1 is a protective factor for atherosclerosis, its role in cholesterol efflux may be dominant." (PMID 32894039, 2020). "The direct role of ABCA1 expression and ANXA1 release in atherosclerosis has been unclear." (PMID 32894039, 2020). "Thus, ANXA1 functions as an anti-inflammatory protein via multiple mechanisms, and many studies suggest that ANXA1 reduces atherosclerosis progression via an anti-inflammatory reaction." (PMID 32894039, 2020). "ANXA1‐based therapeutics would be more beneficial initially in diseases primarily driven by innate immune cells such as atherosclerosis [8, 64, providing a basis for further research into whether this protein could perhaps also be manipulated within the adaptive immune system." (PMID 35146757, 2022). "Therefore, ANXA1 could regulate atherosclerosis development by mediating the transport of cholesterol and the secretion of exosomes and microparticles." (PMID 32894039, 2020). "In chronic inflammatory processes such as atherosclerosis, endothelial‐retargeted AAV9‐transduction of anti‐inflammatory Anxa1 attenuates aortic recruitment of neutrophils and monocytes in atherosclerotic plaques 2 months after transduction." (PMID 35023328, 2022). "Further studies need to focus on the role of ABCA1-mediated ANXA1 efflux and ANXA1-mediated ABCA1 expression in the development of atherosclerosis." (PMID 32894039, 2020). "The ANXA1 mimetics Ac2–26 and CGEN-855A have also been shown to protect against atherosclerosis and MI progression via an anti-inflammatory reaction." (PMID 32894039, 2020). "Among IRF2 targets were the inhibitors of inflammation myocyte enhancer factor 2C (MEF2C) and annexin A1, (ANXA1, also known as lipocortin 1), which was recently shown to decrease atherosclerosis in a mouse model." (PMID 27068706, 2016). "Furthermore, anti-inflammatory/inflammation-regulatory genes (like IL7R, ANXA1, and KLRB1) and pathways (like regulation of IL-2 production) were decreased in CD4+ T cells (T_1, T_2, and T_3) from atherosclerosis compared with those from NC." (PMID 37706320, 2023). "Annexin A1 (AnxA1), the product of ANXA1 gene and also known as lipocortin, is a 37 kDa protein that plays an important role in cardiovascular system, including its pro-resolving function in inflammation related to atherosclerosis and myocardial infarction." (PMID 36313572, 2022). "Many studies have demonstrated that impaired clearance of apoptotic cells promotes the development of atherosclerosis, suggesting that the ICD process by ANXA1 may play a key role in atherosclerosis development." (PMID 32894039, 2020). "The anti-inflammatory and cardio protective effects of CGEN-855A have been investigated by pharmaceutical companies, but the direct effects of ANXA1 on cholesterol transport, exosome and microparticle secretion, apoptotic cell clearance, and ICD in atherosclerosis have rarely been investigated." (PMID 32894039, 2020). "In this review, we focus on the role of ANXA1 in atheroprogression and its novel interaction with ABCA1, which may be useful for providing basic knowledge for the development of novel therapeutic targets for atherosclerosis and cardiovascular disease." (PMID 32894039, 2020). "In addition, ANXA1 may increase ABCA1 expression, but the effect on atherosclerosis development is unknown." (PMID 32894039, 2020). "Pharmacological treatment of inflammation using anxA1 and its N-terminal peptide has been studied in mouse models of neutrophil-dependent edema, cardiac ischemia-reperfusion injury and acute peritonitis, however, hitherto not in atherosclerosis." (PMID 26090792, 2015).
triple-negative breast carcinoma (19 papers, 2015 to 2025). An invasive breast carcinoma which is negative for expression of estrogen receptor (ER), progesterone receptor (PR), and human epidermal growth factor receptor 2 (HER2). "Expression of Annexin A1 (AnxA1) is also associated with poor prognosis in triple-negative breast cancers." (PMID 41149583, 2025). "In contrast, scenarios driven by the binding of AnxA1 to FPRs have associated high AnxA1 levels with poor patient survival and progression in metastatic and triple-negative breast cancers (TNBC)." (PMID 33810523, 2021). "Recently, we reported that ANXA1 is associated with aggressive features of triple-negative breast cancer (TNBC); however, its clinical relevance remains controversial." (PMID 31461932, 2019). "Previous studies have shown Annexin A1 (AnxA1) and Annexin A2 (AnxA2) association with the aggressive behavior of Triple Negative Breast Cancer (TNBC)." (PMID 29416802, 2018). "MDX-124 has been shown to exert potent anti-tumor activity across a broad range of ANXA1-expressing cancer types, including pancreatic and triple-negative breast cancers, both in vitro and in vivo." (PMID 40390008, 2025). "In particular, high ANXA1 expression levels correlate with poorer overall survival in pancreatic and triple-negative breast cancers, two cancers with considerable unmet clinical need." (PMID 38200229, 2024). "It was also reported that AnxA1 plays an essential role in the induction of Tregs in the TME of triple-negative breast cancer models." (PMID 34208346, 2021). "By using the inhibitor of Cathepsin D, Pepstatin A, it was possible to inhibit the amount of cleaved AnxA1, to induce apoptosis, and to decrease the invasion and migration of triple-negative breast cancer cells." (PMID 34208346, 2021). "Targeting ANXA1 abolished Treg-mediated immunosuppression in triple-negative breast cancer." (PMID 36678567, 2023). "Upregulated ANNEXIN A1 promotes cellular invasion in triple-negative breast cancer." (PMID 34340715, 2021). "Triple negative tumors in BRCA1/2 mutated carriers showed a higher ANXA1 expression than triple negative breast cancer patients in the BCAC cohort (84.2 % versus 41.9 %, respectively; P <0.0001)." (PMID 26137966, 2015). "One study showed that triple-negative breast cancer characterized by high Annexin A1 expression and lacking hormone receptor expression, is linked to the presence of mast cells, inflammatory response, and angiogenesis." (PMID 37507468, 2023). "Moreover, the role of AnxA1 in inducing TH2 cells infiltration in pancreatic cancer and in inducing the differentiation and expansion of Tregs in the TME of triple-negative breast cancer models has also been described." (PMID 34571894, 2021).
rheumatoid arthritis (17 papers, 2009 to 2026). A chronic, systemic autoimmune disorder characterized by inflammation in the synovial membranes and articular surfaces. "For example, Annexin A1 showed anti‐inflammatory effects in rheumatoid arthritis by regulating glucocorticoids." (PMID 39507593, 2024). "Additionally, the absence of AnxA1 has been tied to increased disease severity in both rheumatoid arthritis and obstructive pulmonary disease, leading to the hypothesis that treatment with exogenous AnxA1 may help reduce symptoms associated with different inflammatory pathologies." (PMID 31336833, 2019). "In particular, focus is on the process of citrullination of Annexin A1, which takes place within NETs and that mimics, to some extent, other autoimmune conditions, such as rheumatoid arthritis, that are characterized by the presence of anti-citrullinated peptides in circulation." (PMID 29751523, 2018). "Therefore, the finding of citrullination of Arginine 188 in Annexin A1 in NETs is consistent with what is believed to be pertinent to brake tolerance and induce auto-immunity in rheumatoid arthritis." (PMID 29751523, 2018). "Analysis of AnxA1 expression in T cells from patients suffering from rheumatoid arthritis showed higher levels of this protein compared to healthy control volunteers, providing clinical relevance to the role that AnxA1 might play in autoimmune diseases." (PMID 19912648, 2009). "In rheumatoid arthritis (RA), AnxA1 is key in regulating inflammation, primarily through GC treatment." (PMID 41550928, 2025). "In addition, ANXA1 has been described as playing a homeostatic role in cells of the innate immune system and to act as a protective and anti-inflammatory protein in models of rheumatoid arthritis and myocardial infarct by direct inhibition of phospholipase A2." (PMID 24591769, 2014). "There are a few reports concerning ANXA1 and psoriatic arthritis, but no detailed mechanism of ANXA1 in psoriatic arthritis has been elucidated, although a role for ANXA1 in the synovia of rheumatoid arthritis patients has been reported." (PMID 25010044, 2014). "It was demonstrated in animal studies that ANXA1 could alleviate the disease severity of various autoimmune diseases, including inflammatory bowel disease (IBD) and rheumatoid arthritis (RA)." (PMID 35783659, 2022). "The is also evidence for ANXA1 auto-antibody production in rheumatoid arthritis and other chronic inflammatory diseases such as Lupus (Systemic Lupus Erythematosus-SLE) patients which may account for the reduction in biologically available plasma ANXA1 protein." (PMID 35684160, 2022).
viral infection (17 papers, 2011 to 2025). "To further elucidate the mechanism underlying reduced viral replication upon AnxA1 treatment, we checked viral infection efficacy and replication properties in murine primary epithelial lung cells." (PMID 31398292, 2019). "For instance, in preclinical models of infectious diseases, AnxA1 limits excessive inflammation during bacterial and viral infections." (PMID 40956847, 2025). "It was demonstrated that the levels of AnxA1 increased in a time-dependent manner in vitro during different viral infections, such as HSV, Sendai virus, Seneca valley virus and FMDV." (PMID 37190040, 2023). "AnxA1 was shown to be involved in the antithrombotic response and response to viral infection, and its role in suppressing inflammation was demonstrated in AnxA1 knockout mice (AnxA1−/−) based on glucocorticoid-induced activation of innate immune cells." (PMID 36766501, 2023). "While this is potentially true for some viral infections, including arbovirus diseases, other viruses have evolutionarily developed strategies to hijack the AnxA1/FPR2 axis, to infect and replicate more effectively." (PMID 37190040, 2023). "Studies in pre-clinical models have been instrumental to uncover AnxA1 protective or detrimental effects in the context of viral diseases." (PMID 37190040, 2023). "In this review, we provide an in-depth view of the role of AnxA1 during viral infections, from pre-clinical to clinical studies." (PMID 37190040, 2023). "Harnessing the pro-resolution actions of AnxA1 holds promise as a therapeutic strategy to control the severity of the clinical presentation of viral infections." (PMID 37190040, 2023). "An interesting remark, based on the current literature on AnxA1 and viral disease, is that viruses that have co-evolved closely with humans, such as seasonal influenza virus and HSV-1, were shown to exploit the AnxA1 pathway for replication." (PMID 37190040, 2023). "Viral diseases are often related to dysregulated inflammatory responses and, therefore, one would assume that AnxA1 would be an interesting therapeutic strategy." (PMID 37190040, 2023). "The present study observed that viral infection increased annexin-A1 (ANXA1) expression, and ANXA1 then promoted RNA virus-induced IFN-I production." (PMID 35604142, 2022). "Yet, this protective effect of AnxA1 against viral infection also requires the AnxA1/FPR2 signaling axis to increase alveolar macrophages, which are decisive factors in the host defence against pathogens." (PMID 33810523, 2021). "Because the contribution of this signaling axis in viral infections is undefined, we investigated AnxA1-mediated FPR2 activation on influenza A virus (IAV) infection in the murine model." (PMID 31398292, 2019). "Therefore, in the next sections, we will discuss what is currently known about the role of AnxA1 during viral infections." (PMID 37190040, 2023). "In this regard, one would assume that AnxA1 is mainly protective in the context of viral diseases." (PMID 37190040, 2023). "In addition, this review discusses the therapeutic potential for AnxA1 and AnxA1 mimetics in treating viral infections." (PMID 37190040, 2023). "In the present study, we found that viral infection increased ANXA1 expression." (PMID 35604142, 2022). "To verify whether the expression level of ANXA1 is correlated with viral infection, we assessed ANXA1 protein expression and mRNA levels after viral infection." (PMID 35604142, 2022). "More than 20 of the differentially expressed proteins were directly associated with immunity, apoptosis, tumour development and viral infection and replication, including macrophage migration inhibitory factor (MIF), heat shock protein 90 alpha (Hsp90alpha), and annexin-A1 (Anx-A1)." (PMID 23116199, 2012).
viral infection (continued). "Using genetic ablated mice for AnxA1 and AnxA1-mimetic peptide (Ac2-26), our research group and others have shown the importance of this protein in controlling inflammation and promoting resolution in various preclinical models, such as bacterial and viral infections and aseptic inflammation." (PMID 40956847, 2025). "Therefore, the role of AnxA1 during viral infections is complex and dynamic." (PMID 37190040, 2023). "However, AnxA1 has been less investigated in the context of viral infections." (PMID 36078125, 2022). "At these sites, AnxA1 contributes to the regulation of endo- and exocytosis, signal transduction, cellular metabolism, and cytoskeletal rearrangements, all relevant for proliferation, differentiation, migration, survival, but also repair, inflammation and viral infection." (PMID 33810523, 2021). "Genes in this signature code for proteins that are viral infection restricting factors (e.g. Ifitm1, Ifitm3, Gbp7), that protect against cellular or environmental stress (e.g. Abcb1a, Car2, Ern1, Serpina3g) or that regulate immune activation processes (e.g. Fgl2, Anxa1, Havcr2)." (PMID 27883012, 2016). "For example, annexin A1 (ANXA1) was confirmed to play a detrimental role in influenza infection and positively regulated virus titers in viral infection experiments using mice." (PMID 31001125, 2019). "To analyze the role of the interacting proteins during viral infection, we examined previously published proteomic databases and found that EEF2, ANXA1, ANXA5, SLADRA, CLTA, and FTH1 were significantly enriched and FTH1 was notably upregulated in ASFV-infected PAMs." (PMID 40661982, 2025). "Not surprising, therefore, Anxa1 gene knockout (KO) mice have been shown to be protected from viral infection." (PMID 36233010, 2022). "The absence of an increase in ANXA1-SER in the HPV- epithelium samples compared to the HPV- carcinoma tissues probably arises from the absence of an inflammatory reaction to the viral infection." (PMID 24782913, 2014).